TUFT1 (tuftelin 1)
Description:
Involved in the structural organization of the epidermis. Involved in the mineralization and structural organization of enamel.
Synonyms: WHSF
Tractability: Antibody: UniProt places it where antibodies can reach, with medium confidence; its Gene Ontology location is reachable by antibodies, with medium confidence. PROTAC: ubiquitination databases record sites on it.
Gene: Protein-coding gene on chromosome 1 (151,540,305 to 151,583,583, forward strand). Ensembl gene ENSG00000143367.
Subcellular location: Secreted
Subcellular location (Human Protein Atlas): Vesicles; Predicted to be secreted
Gene Ontology:
Molecular function: protein binding; structural constituent of skin epidermis; structural constituent of tooth enamel
Biological process: bone mineralization; odontogenesis
Cellular component: cytoplasm; extracellular region; I band; RNA polymerase II, core complex
Genetic constraint (gnomAD): Loss-of-function variants: 42 observed, 54.8 expected, observed/expected ratio (o/e) 0.77, 90% interval 0.6 to 0.99. The upper end of that interval is the gene's LOEUF score, 0.99, which puts it in group 4 of 6, group 1 being the genes least tolerant of losing a copy. Missense variants: 459 observed, 482.28 expected, observed/expected ratio (o/e) 0.95, 90% interval 0.88 to 1.03. Synonymous variants: 166 observed, 172.83 expected, observed/expected ratio (o/e) 0.96, 90% interval 0.85 to 1.09.
Homologues: Orthologues: chimpanzee TUFT1 (98% identical), macaque TUFT1 (98% identical), mouse Tuft1 (89% identical), rat Tuft1 (88% identical), pig TUFT1 (87% identical), rabbit TUFT1 (87% identical), dog TUFT1 (86% identical), guinea pig TUFT1 (79% identical), tropical clawed frog tuft1 (39% identical), zebrafish tuft1a (32% identical). Paralogues in human: MYZAP (26% identical), CCDC68 (18% identical), POLR2M (8% identical).
Diseases named in the same sentence as TUFT1 in open-access papers:
TUFT1 is named in the same sentence as 32 diseases in open-access papers, as found by Europe PMC text mining. Sharing a sentence is not in itself a finding about the gene and the disease. The quoted sentences say what the papers report.
hepatocellular carcinoma (13 papers, 2020 to 2025). A malignant tumor that arises from hepatocytes. "Overexpressed TUFT1 has been observed in a number of malignancies including hepatocellular carcinoma (HCC), breast cancer, thyroid carcinoma, and osteosarcoma." (PMID 39925739, 2025). "To determine the relevance of PEA15, PPP1CA and TUFT1 in hepatocellular carcinoma in vivo, we analyzed three publically available expression datasets of primary HCCs." (PMID 34976171, 2022). "In the following, we focused on PEA15, PPP1CA and TUFT1 because they showed a strong regulation in qRT-PCR and literature research of these genes indicated promising approaches for the treatment of hepatocellular carcinoma." (PMID 34976171, 2022). "In this study, we comprehensively investigated the impact of miR-449a-5p and its target genes PEA15, PPP1CA and TUFT1 on the effects of sorafenib treatment in hepatocellular carcinoma." (PMID 34976171, 2022). "In the publication at hand, we focus on the characterization of the miR-449a-5p targetome and analyze the impact of miR-449a-5p and its target genes PEA15, PPP1CA and TUFT1 on the efficacy of sorafenib in hepatocellular carcinoma." (PMID 34976171, 2022). "In hepatocellular carcinoma, hypoxia promotes TUFT1 expression, which activates the Ca2+/PI3K/AKT pathway to promote cancer growth and metastasis." (PMID 35280516, 2022). "Recently, TUFT1 expression is reported to be elevated in several types of cancers including hepatocellular carcinoma (HCC), breast cancer, thyroid carcinoma and osteosarcoma." (PMID 34257606, 2021). "TUFT1 was initially found to play an important role in the development and mineralization of tooth enamel and was later discovered in many cancerous tissues, including pancreatic cancer and hepatocellular carcinoma." (PMID 35205261, 2022). "Co-treatment with KPA also decreased the expression of genes, regulating the progression of fibrosis (e.g., COL6A3, AEBP1, SPARC, TNC, LAMB1, BGN) and hepatocellular carcinoma (e.g., COL4A1, COL4A2, TUFT1, VCAN, NID1)." (PMID 39404414, 2024). "Elevated TUFT1 expression regulates CDH1 and vimentin expression through the hypoxia-inducible factor 1–SNAI1 signaling pathway in pancreatic and hepatocellular cancer metastasis." (PMID 34455105, 2021). "Our findings demonstrate that PEA15, PPP1CA and TUFT1 are frequently overexpressed in HCC and that patients with hepatocellular carcinoma may benefit from the repression of these genes." (PMID 34976171, 2022).
breast carcinoma (9 papers, 2017 to 2025). "Recent studies have shown that TUFT1 is an oncoprotein that promotes proliferation, metastasis, and drug resistance in breast cancer cells and is associated with worse clinical status and poor prognosis." (PMID 41022752, 2025). "Afterward, we explored the effects and potential mechanisms underlying the activity of TUFT1 in breast cancer cells in vitro and in vivo." (PMID 29088838, 2017). "In order to further study the mechanisms underlying TUFT1-induced effects in breast cancer, we used microarray analysis of TUFT1-knockdown MDA-MB-231 cells, and found significant differences in the expression of hundreds of genes, in comparison with that in the control cells." (PMID 29088838, 2017). "Upregulation of the NEK2/TUFT1 axis in breast cancer is associated with poor outcomes, implying that for the cancer cell population the disadvantage conferred by TUFT1 hyperphosphorylation on cell proliferation may be overcome by its advantage of increasing CA and CIN." (PMID 41022752, 2025). "However, the mechanisms underlying cell cycle arrest and apoptosis induced by TUFT1 downregulation in breast cancer cells remain unclear, and they should be further investigated." (PMID 29088838, 2017). "We further assessed the correlation between NEK2/TUFT1 expression and the overall survival (OS) of patients with breast cancer based on Kaplan-Meier Plotter databases." (PMID 41022752, 2025). "In this study, we identified a novel mechanism of TUFT1 in the regulation of breast cancer progression." (PMID 41022752, 2025). "Data from clinical breast cancer samples indicate that the combined detection of TUFT1 and NEK2 expression reflects tumor malignancy and patient survival with higher precision." (PMID 41022752, 2025). "NEK2 expression negatively correlated with OS only in the TUFT1 high-expression group, indicating that NEK2 drives breast cancer progression by regulating TUFT1." (PMID 41022752, 2025). "All phenotypes were rescued by transient siRNA-resistant exogenous TUFT1 transfection, indicating that TUFT1 suppresses CA in breast cancer cells." (PMID 41022752, 2025). "In general, patients with breast cancer with hyperphosphorylated TUFT1 exhibited an increased rate of lymph node metastasis and reduced OS, consistent with the consensus that high levels of CIN are related to poor clinical outcome." (PMID 41022752, 2025). "Next, we sought to investigate the effects of TUFT1 phosphorylation on clinical outcome in patients with breast cancer." (PMID 41022752, 2025). "Overall, the phosphorylation status of TUFT1 is essential for coordinating centrosome number and cell proliferation in cervical and breast cancers." (PMID 41022752, 2025). "In summary, upregulation of the NEK2/TUFT1 axis predicts poor outcome in patients with breast cancer." (PMID 41022752, 2025). "Another lncRNA, differentiation antagonizing non-protein coding RNA (DANCR), which can be activated by tuftelin 1 (TUFT1), was upregulated in breast cancer tissues." (PMID 36613528, 2022). "We similarly found that the oncogenic protein TUFT1, whose expression is increased in breast cancer tissues, is also upregulated during RPE-EMT." (PMID 34455105, 2021). "Tuft1 plays an important regulatory role in the survival of breast cancer cells; however, its role in regulating TNBC metastatic potential has not been well-characterized." (PMID 31338333, 2019). "Our previous study found that inhibition of TUFT1 expression in breast cancer cells inhibited proliferation, affected the cell cycle, and induced apoptosis." (PMID 31338333, 2019). "The TCGA RNA Seq data showed that TUFT1 was significantly upregulated in over 67.92% of breast cancer tissues (n = 106) compared with adjacent normal breast tissues (P=7.77E-55)." (PMID 29088838, 2017). "This is in accordance with the previously obtained results showing that TUFT1 is overexpressed in breast cancer samples." (PMID 29088838, 2017).
breast carcinoma (continued). "Additionally, we showed that the alterations of the regulatory mechanisms affecting the expression of many oncogenes and the activation of cancer-related pathways may represent the mechanisms underlying TUFT1-dependent development and progression of breast cancer." (PMID 29088838, 2017). "In conclusion, this is the first study linking TUFT1 expression and activity to breast cancer prognosis, and a positive correlation between TUFT1 expression and breast cancer cell proliferation and apoptosis was established for the first time here." (PMID 29088838, 2017). "This is the first investigation into the role and mechanisms of TUFT1 in breast cancer, as far as we know." (PMID 29088838, 2017). "According to our results, TUFT1 protein levels were elevated in breast cancer tissues compared with adjacent normal tissues." (PMID 29088838, 2017). "Gene chip and functional pathway analyses showed that TUFT1 expression is related to a variety of typical cancer-related pathways in human breast cancer cells." (PMID 29088838, 2017). "So, more studies will be developed to explore the relationship between TUFT1 and these genes in breast cancer." (PMID 29088838, 2017). "Overall, TUFT1 exerts oncogenic roles through multiple mechanisms in breast cancer." (PMID 41022752, 2025). "In addition, in breast cancer, TUFT1 promotes metastasis and chemoresistance through Rab5/Rac1 pathway." (PMID 34257606, 2021). "Therefore, the aim of this study was to investigate the alterations in the expression and biological functions of TUFT1, and correlate these findings with breast cancer patient prognosis." (PMID 29088838, 2017). "The obtained results suggest that TUFT1 may represent a novel breast cancer marker and a potentially effective therapeutic target." (PMID 29088838, 2017). "TUFT1 was shown to be expressed mainly in cytoplasm and cytomembrane of breast cancer cells." (PMID 29088838, 2017). "TUFT1 may represent a novel molecular marker and potent therapeutic target for breast cancer treatment." (PMID 29088838, 2017). "We proved both human specimens studies and cell line studies, that TUFT1 expression levels are increased in breast cancer samples, and the increased expression of TUFT1 was shown to be positively correlated with tumor size, histological grade, lymph node metastasis rate, and poor prognosis." (PMID 29088838, 2017). "Although the follow-up period was relatively short, TUFT1 overexpression was negatively correlated with the patient survival rate, indicating that TUFT1 may be involved in breast cancer progression, and serve as a prognostic factor for this type of cancer." (PMID 29088838, 2017). "Meanwhile, within the TUFT1 high-expression group, patients with hyperphosphorylated TUFT1 exhibited reduced OS, implying that for the entire breast cancer cell population, the disadvantage of TUFT1 hyperphosphorylation on cell proliferation may be overcome by its advantage of increasing CA and CIN." (PMID 41022752, 2025). "However, the precise role of TUFT1 in breast cancer (BC), including the mechanics of TNBC's metastasis remain unclear." (PMID 31338333, 2019). "We mainly focused on cervical and breast cancers for subsequent investigations because both NEK2 and TUFT1 have been reported to promote the progression and chemoresistance of these two cancers." (PMID 41022752, 2025). "TUFT1 is recently shown to be elevated in HCC and its elevation in expression promotes the progression of several types of cancers including HCC, breast cancer, thyroid carcinoma and osteosarcoma." (PMID 34257606, 2021). "The results shown that the expression of TRRERF1, PER1, TUFT1, CCND1, and ENPP2 genes was significantly different in breast cancer and adjacent tissues (p < 0.0001)." (PMID 33365308, 2020). "Further in vitro studies showed that the inhibition of TUFT1 expression in T-47D and MDA-MB-231 breast cancer cells significantly affected cell proliferation, induced apoptosis, and led to G1-phase cell cycle arrest." (PMID 29088838, 2017).
breast carcinoma (continued). "In addition, TUFT1 is phosphorylated by NIMA-related kinase 2 (NEK2), and the phosphorylation status of TUFT1 is essential for coordinating centrosome number and cell proliferation in cervical and breast cancers." (PMID 41022752, 2025).
pancreatic cancer (8 papers, 2017 to 2025). "As for its roles in EMT, a publication has demonstrated that depletion of endogenous TUFT1 impacts the expression levels of EMT-associated proteins (E-cadherin and Vimentin) in pancreatic cancer." (PMID 36797791, 2023). "Cell function experiments further confirmed that TUFT1 depletion reduced proliferation and metastasis of pancreatic cancer cells, and impaired various proteins expression related to epithelial-mesenchymal transition." (PMID 31338333, 2019). "Zhou and colleagues described a role of TUFT1 in the metastasis of pancreatic cancer cells by increasing hypoxia-inducible factor-1-Snail signaling which promotes EMT22." (PMID 29423269, 2018). "Bin Zhou showed that TUFT1 is overexpressed in pancreas cancer (PC) tissues compared with adjacent normal pancreas tissues, and TUFT1 expression is significantly associated with lymph node metastasis and advanced PC stage." (PMID 29088838, 2017). "TUFT1 could inhibit the growth of pancreatic cancer cells, but there are few studies on the effect of TUFT1 on GC." (PMID 36797791, 2023). "Moreover, a publication concerning to pancreatic cancer has illustrated that TUFT1 expression is induced in the disease progression and TUFT1 has the capacity to accelerate growth, metastasis, and epithelial-mesenchymal transition of cancer cells." (PMID 36797791, 2023). "Similarly, TUFT1 regulates metastasis in pancreatic cancer through epithelial-mesenchymal transformation induced by HIF1-Snail." (PMID 35635094, 2022). "Another study had found that TUFT1 may regulate epithelial mesenchymal transition by affecting HIF1-Snail signaling pathway in pancreas cancer." (PMID 29088838, 2017). "The findings also show that ALDH3B1, PTGES, and TUFT1, the downstream genes of ZIC5, contribute to gemcitabine resistance in pancreatic cancer cells." (PMID 40318167, 2025). "In our experiments, stable overexpression of RIOK3 (even in combination with TUFT1) did not restore the effect of ZIC5 suppression in MiaPaca‐2 cells, suggesting that other ZIC5 downstream genes also contribute to pancreatic cancer survival." (PMID 40318167, 2025).
cervical cancer (6 papers, 2021 to 2025). A primary or metastatic malignant neoplasm involving the cervix. "The circ_0074269-miR-485-5p-TUFT1 axis can increase the resistance of cervical cancer to cisplatin by up-regulating the expression of TUFT1." (PMID 41217541, 2025). "In the development of cervical cancer, up-regulating TUFT1 is effective in increasing proliferation and reducing apoptosis of drug-resistant tumor cells." (PMID 36797791, 2023). "Hsa_circ_0074269 increased cisplatin resistance via mediating miR-485-5p and TUFT1 in cervical cancer." (PMID 36438563, 2022). "Exosomal lncRNA HNF1A-AS1 enhanced cisplatin resistance via elevating the expression of TUFT1 by sponging microRNA-34b axis in cervical cancer cells." (PMID 36438563, 2022). "Another study indicated that lncRNA HNF1A-AS1 up-regulated the expression of TUFT1 by competing with miR-34b, thus reducing the sensitivity of cervical cancer cells to CDDP." (PMID 34746018, 2021). "For example, the lncRNA HNF1A-AS1 carried by exosomes upregulates the expression of tuftelin 1 (TUFT1), promoting proliferation and drug resistance in cervical cancer cells." (PMID 38540273, 2024).
dental caries (6 papers, 2017 to 2025). The decay of a tooth, in which it becomes softened, discolored, and/or porous. "The C/C genotype of the TUFT1 rs2337359 polymorphism appears to be associated with increased susceptibility to dental caries, as measured by the DMFT index, suggesting its role in the aetiology of dental caries in the study population." (PMID 40869069, 2025). "The C/C genotype in the TUFT1 rs2337359 polymorphism was found to be a risk factor for dental caries, as indicated by DMFT values in the study population." (PMID 40869069, 2025). "However, none of the TUFT1 haplotypes showed any significant association with dental caries after Bonferroni correction (p > 0.05)." (PMID 36422720, 2023). "Genetic association studies of dental caries have suggested that caries may be influenced by variations in enamel formation genes, such as ameloblastin (AMBN), amelogenin (AMELX), enamelin (ENAM), matrix metalloproteinase 20 (MMP20), tuftelin (TUFT1), and tuftelin-interacting protein 11 (TFIP11)." (PMID 29163197, 2017). "Even though TUFT1 function has not been fully clarified yet, sequence changes in the TUFT1 gene can interfere with other gene or protein interactions, thereby influencing, among other things, the development of dental caries." (PMID 36422720, 2023). "Aside from TUFT1 and DEFB1, the loci reported here have not been associated with dental caries in previous studies, which have largely comprised Caucasian individuals." (PMID 31533690, 2019). "In this case–control study, 15 SNPs in ALOX15, AMBN, AMELX, KLK4, TFIP11, and TUFT1 genes were analyzed in 150 children with primary dentition and 611 children with permanent teeth with/without dental caries from the European Longitudinal Study of Pregnancy and Childhood (ELSPAC) cohort." (PMID 36422720, 2023).
gastric cancer (5 papers, 2018 to 2025). A primary or metastatic malignant neoplasm involving the stomach. "We previously reported that SUMOylation of TUFT1 is essential for AKT/mTOR pathway activation in gastric cancer cells." (PMID 41022752, 2025). "Consistently, the expression of TUFT1 correlated with poor prognosis in lung, breast and gastric cancers." (PMID 29423269, 2018). "The miR-128-3p can inhibit the progression of gastric cancer by targeting TUFT1." (PMID 41217541, 2025). "In gastric cancer cells, the AKT/mTOR signaling pathway was hindered by TUFT1 SUMOylation, leading to promotion of cell proliferation and migration." (PMID 37906341, 2023). "To assess the involvement of TUFT1 in amino acid signaling, we utilized MKN45 human gastric cancer cells, in which the NPRL3 gene is homozygously deleted, and Kato III as control human gastric cancer cells." (PMID 29423269, 2018).